IL1B (interleukin 1 beta)
Diseases named in the same sentence as IL1B in open-access papers (continued):
Sharing a sentence is not in itself a finding about the gene and the disease.
colitis (continued). "Increased severity of colitis was also evidenced by increased tissue levels of IL-1β and TNFα (p < 0.05) following DSS administration." (PMID 31444382, 2019). "Considerable evidence supports the idea that NLRP3 inflammasome plays a pro-inflammatory role in colitis pathology, and blockage of IL-1β or IL-18 has been reported to reduce colitis." (PMID 30823406, 2019). "During colitis, infiltrating monocytes are redirected toward a more pro-inflammatory macrophage phenotype, with elevated production of IL-1β, IL-23, and tumor necrosis factor (TNF)." (PMID 31031776, 2019). "In summary, our findings indicate that TREM-1 protects mice against acute DSS-induced colitis by promoting M1 macrophage polarization and IL-1β production, which contributes to IL-22 production by ILC3 that restores epithelial barrier integrity." (PMID 31189465, 2019). "TREM-1 increases IL-1β production by M1 macrophages during DSS-induced colonic inflammation and thereby influences ILC3-mediated IL-22 production." (PMID 31189465, 2019). "Mice of the DSS + PBS group lost weight over time, and weight loss in mice with colitis that were treated with M2 macrophages (DSS + IL-13-cell; DSS + IL-10-cell; and DSS + IL-1β-cell groups) was alleviated." (PMID 31749791, 2019). "Pro-inflammatory cytokines, such as TNF-α, IL-1β and IL-6, play important roles in colitis development." (PMID 29495327, 2018). "Not only were IL-1β+ monocytes more numerous in DSS colitis, but the proportion of monocytes expressing IL-1β increased significantly (1.9-fold to 51.7% of all monocytes), which was greater than any other IL-1β expressing myeloid population." (PMID 30542349, 2018). "Mirroring this improvement in colitis, Rag2−/−hLrh1IEC-TG animals showed a decreased inflammatory cytokine profile, with lower intestinal expression of TNFα, IL-1β, and IL-6, and a corresponding increase in the anti-inflammatory cytokine IL-10." (PMID 30305617, 2018). "Further, IL-1β was the primary cytokine elevated in Rev-erbα−/− mice at the early phase of DSS-colitis." (PMID 30315268, 2018). "Rats with colitis displayed a significant increase in colonic IL-1β levels (27.7 ± 4.2 ng/mg tissue), as compared with values estimated in control animals (9.2 ± 0.9 ng/mg tissue)." (PMID 30559669, 2018). "In this study, protein levels of TNF-α and IL-1β in colons of colitis mice were markedly increased, and alpinetin (7.5, 15, 30 mg/kg) exerted obvious inhibition." (PMID 30166541, 2018). "Together, our murine and human data suggest that monocyte recruitment, and systemic priming of monocyte IL-1β release, are key components involved in escalation of colon inflammation in colitis." (PMID 30542349, 2018). "To further explore the effect of MCC950 on NLRP3 inflammasome activation in colitis, we investigated the release of IL-1β in treated Winnie colonic tissue explants by ELISA." (PMID 29872077, 2018). "Mice lacking TPH-2 (neuronally restricted expression) exhibit increased severity of disease accompanied by elevated TNF-α, IL-1β, and IL-6 levels during experimental colitis compared with wild-type mice." (PMID 30177522, 2018). "P. mirabilis stimulates robust IL-1β production in response to dextran sulfate sodium-induced colitis, mediated by the NOD-like receptor family pyrin domain-containing 3 inflammasome activation." (PMID 29352191, 2018). "The pro‐inflammatory cytokines (IL1A, IL1B and IL‐6), neutrophils and bacterial infiltration were significantly increased in CD11c‐Cre+Rab32f/f mice with colitis induced by DSS." (PMID 30338217, 2018). "Here we demonstrate that macrophage specific deletion of WASP is sufficient to drive enhanced expression IL-1β and IL-23, which promotes generation of pathogenic IL-17+IFN-γ+ CD4+ T cells and colitis." (PMID 29725003, 2018). "The results indicated that the infusion of fAT-MSCs had inhibitory effects on the expression of TNF-α, IL-1β, IFN-γ, and IL-6, which are classically associated with DSS-induced colitis, in the colonic tissue." (PMID 30453939, 2018).
colitis (continued). "EtOH significantly elevated IL-6 mRNA in colonic mucosa, and DSS-induced colitis elevated mRNA for IL-1β, TNFα and IL-6." (PMID 30389960, 2018). "The administration of obestatin at all doses used partly reversed the colitis-evoked increase in mucosal concentration of IL-1β, and this effect was statistically significant after obestatin administered at doses of 8 or 16 nmol/kg." (PMID 29865176, 2018). "Consistently, the expression of the proinflammatory cytokine IL-1β was downregulated by B. fragilis colonization in our animal model of DSS-induced colitis." (PMID 30429227, 2018). "The primary macrophage cells isolated from Winnie had a higher secretion of IL-1β in comparison to C57BL/6 indicating active colitis in Winnie." (PMID 29872077, 2018). "To investigate changes in pro-inflammatory cytokine levels in a DSS-induced colitis model, we measured IL-1β, IL-6, and TNF-α levels at the mRNA (RT-PCR) and protein (ELISA) levels in the colon." (PMID 29610929, 2018). "Pro-inflammatory cytokines TNFα and IL-1β were used in the present study to induce a colitis-like state in the human colonic mucosa and Caco-2 cells." (PMID 30127744, 2018). "We found that alpinetin (30 mg/kg) showed well reduction of DAI scores, MPO activity, shortening of colon length, histological changes and levels of TNF-α as well as IL-1β in colons of colitis mice, which was restored by CH223191 (10 mg/kg)." (PMID 30166541, 2018). "This is an important finding as this indicates the percentage of canonical and non-canonical NLRP3 inflammasome contribution to the overall IL-1β in the spontaneous colitis colon of Winnie mice." (PMID 29872077, 2018). "In this study, we demonstrated that B. fragilis treatment prevented the development of acute dextran sulfate sodium (DSS)-induced colitis by partly inhibiting IL-1β and C-C chemokine receptor 5 (CCR5) expression." (PMID 30429227, 2018). "In fact, pro-inflammatory cytokines (TNF, IL-1β and IL-6) contributed to tissue destruction and colitis perpetuation." (PMID 30592734, 2018). "EtOH feeding or DSS-induced colitis significantly elevated mRNA for IL-1β, TNFα and IL-6 genes in ileal mucosa." (PMID 30389960, 2018). "In a murine T-cell transfer or TNBS model of colitis, expression of IL-1β, IL-6, tumor necrosis factor alpha (TNF-α), and IL-10, which are involved in inflammation, was regulated by B. fragilis." (PMID 30429227, 2018). "Mice engineered to lack components of the serotonergic system have revealed 5-HTs participation in gut disease: TPH1−/− mice exhibited reduced severity of chemical-induced colitis and an accompanying reduction in IL-1β, IL-6, and TNF-α." (PMID 30177522, 2018). "Here we go further, having shown that during DSS colitis, macrophages, DCs and neutrophils in the colon can produce IL-1β in addition to monocytes." (PMID 30542349, 2018). "As such, the impact of colon monocytes on inflammation during DSS colitis is likely a compound effect of increased per cell IL-1β production along with increased recruitment." (PMID 30542349, 2018). "In this study, we found that supplemented with Farrerol significantly suppressed the production of pro-inflammatory cytokines TNF-α, IL-6 and IL-1β in TNBS-induced colitis mice." (PMID 30011811, 2018). "The observed increases in the levels of defensin, TNF-α, and IL-1β, -17α, and -22 in mice with colitis relative to healthy controls were reversed by MI-2 treatment." (PMID 30249750, 2018). "Our presented study showed that TNBS-induced colitis led to an increase in IL-1β concentration in the damaged tissue, and this effect was still observed 14 days after administration of TNBS." (PMID 29865176, 2018). "Plasma levels of TNFα, IL-1β and IL-6 in the plasma were significantly increased by EtOH feeding and colitis." (PMID 30389960, 2018). "Out results demonstrated that the levels of TNF-α, IL-1β, and IL-6 were markedly downregulated in the colonic LP in colitis mice with GLP treatment." (PMID 29888292, 2018).
colitis (continued). "In the present study, we found that SAA-administrated colitis rats showed decreased expression of the pro-inflammatory cytokines IL-1β, IL-6, and MCP-1." (PMID 29921812, 2018). "Consistent with previous reports, we observed that TNBS-induced colitis invariably promoted inflammation in the colon with elevated levels of IL-1β, IL-6, TNF-α and an increased expression of JAK2, STAT3, and p-STAT3." (PMID 30042683, 2018). "The molecular characterization resulted in identification of Il1β as the major elevated cytokine during early phases of colitis." (PMID 28796256, 2017). "We confirmed that reactivation of colitis significantly increased colonic level of pro-inflammatory cytokines IL-6, IL-1β, and TNF- α and decreased level of colonic anti-inflammatory cytokine TGF-β, but IL-10 levels were not affected." (PMID 28871257, 2017). "Monocytes and macrophages regulate gut inflammation and the majority of tissue infiltrating cells following reactivation of quiescence colitis are M1 macrophage and are the main source of IL-6, IL-1β, and TNF- α." (PMID 28871257, 2017). "The colitis mice given a neutralizing S100a9 antibody produced less inflammatory cytokines, such as Tnfα, Il1β, Il6, Il17a, Ifnγ, and Il12a, all of them are master regulators of inflammation and tumorigenesis." (PMID 29326691, 2017). "According to our data, baicalein effectively inhibited the mRNA expression of iNOS, ICAM-1, COX-2, MCP-1, TNF-α and IL-1β in the colon of TNBS-colitis mice." (PMID 29180692, 2017). "It is well known that the increased pro‐inflammatory cytokines (TNF-α, IL-1β and IL-6) observed in our model of colitis amplify the inflammatory cascade and result in intestinal tissue damage in patients with UC." (PMID 28270147, 2017). "We observed that IL-1β was increased in both TNBS-induced colitis mice and LPS-induced THP-1 human macrophage cells." (PMID 29180692, 2017). "Accordingly, the increased mRNA level of IL-1β was observed in the colonic tissues of TNBS-colitis mice as well as in LPS-treated THP-1 human macrophage cells." (PMID 29180692, 2017). "It was recently shown that infectious triggers such as influenza lung infection and colitis trigger an IL-1β-induced Th17 differentiation and promote arthritis induced by KRN transgenic T cells." (PMID 28645307, 2017). "In murine models, PTPN22 deficiency results in pronounced colitis, increased NLRP3 phosphorylation, but reduced levels of mature IL-1β." (PMID 28561062, 2017). "Consistent with a role for MAVS in NLRP3 activation, MAVS-deficient mice exposed to dextran sodium sulphate (DSS)-induced colitis fail to upregulate IL-1β." (PMID 29120406, 2017). "L. reuteri can suppress intestinal inflammation in a trinitrobenzene sulfonic acid-induced mouse colitis model via downregulation of gene expression of mucosal cytokine IL-6 and IL-1β in the colon." (PMID 28943876, 2017). "While numerous studies indicate the protective role of inflammasomes and IL-18 in DSS-induced colitis, recent studies demonstrate inflammasome-mediated IL-1β drives chronic inflammation in IL-10 KO mice and in human patients with IL-10R deficiency." (PMID 28955343, 2017). "Expression patterns of three subpopulations from mLNs of WT colitis mice were also compared, the mRNA expression levels of IL-17, TNFα, and IL-1β were also much higher in CD11b+CD169+ macrophages than those in the other two subpopulations." (PMID 28694804, 2017). "IL-37b-tg mice protect from DSS-induced colitis, characterized by decreasing clinical disease score, histological score, and TNFα and IL-1β production, but increasing IL-10 production in colon tissue." (PMID 28420941, 2017). "Treatment with IL-1 receptor antagonist or caspase-1 inhibitors suppressed IL-1β and IL-17 production, thus ameliorating spontaneous colitis in IL-10−/− mice." (PMID 28179906, 2017).
colitis (continued). "Anakinra blocks both IL-1α and IL-1β, but in the mouse model described, experimental specific IL-1α antibodies were significantly more efficacious in reducing severity of colitis compared to external IL-1 receptor antagonist (IL-1RA)." (PMID 28288653, 2017). "Inhibition of CSF-1 suppressed DSS-induced colitis due to diminished immune cell infiltration of T cells and macrophages in colon tissue and reduction of TNFα, IL-1β and IL-6 levels." (PMID 29261815, 2017). "Herein, we found that celastrol significantly ameliorated colitis carrying the suppression of cleaved caspase-1 and IL-1β secretion." (PMID 28978034, 2017). "TNF-α and IL-1β are the most important cytokines that are present in colon tissues and involved in the pathogenesis of colitis." (PMID 28574825, 2017). "mRNA expression of iNOS, ICAM-1, MCP-1, COX-2, TNF-α and IL-1β was remarkably induced in the colonic tissues of TNBS-colitis mice." (PMID 29180692, 2017). "Decarine reduced IL-6 and IL-8 production in TNF-α+IL-1β-induced Caco-2 cells, which indicated anti-inflammatory activity on human colon cells and justified the use of Maqian as a remedy for colitis." (PMID 28383530, 2017). "Results obtained in our present study have demonstrated that acetic acid-induced colitis led to a tenfold and sixfold increase in IL-1β concentration in colonic mucosa at the 7th an 14th day after induction of this inflammation, respectively." (PMID 26798415, 2016). "Conversely, the treatment of ITGA4 antibodies in combination with conventional therapies alleviated colitis by suppression of IL-1β and iNOS in mouse models." (PMID 27111221, 2016). "The next interesting finding originated from our present study is the influence of intraperitoneal administration of obestatin on the concentration of interleukin-1β (IL-1β) and myeloperoxidase activity in colonic mucosa of animals with colitis." (PMID 26798415, 2016). "Seven days after induction of colitis in rats treated i.p. with saline, almost a seven-fold increase in mucosal concentration of IL-1β in the colon was observed." (PMID 27598133, 2016). "It has been reported that RIPK3 within dendritic cells (DCs) promotes injury-induced inflammation and tissue repair in the dextran sulfate sodium (DSS) model of colitis, partly through an IL-23, IL-1β, and IL-22 axis." (PMID 27344176, 2016). "Here we report that HBO2 significantly reduces severity of DSS-induced colitis, as evidenced by the clinical features, histological assessment, impaired immune cell expansion and mobilization, and reversal of IL-1β, IL-2, and IL-6 gene expression." (PMID 27656047, 2016). "The effects of Sal B on the recurrence of colitis induced by interleukin-1 beta (IL-1β) were also investigated based on its protective effects on epithelial barrier function." (PMID 27303297, 2016). "Fourteen days after induction of colitis, IL-1β and TNF-α concentration in colonic mucosa in rats treated with ghrelin was similar to that observed in animals without induction of colitis." (PMID 27598133, 2016). "DSS-colitis increased mRNA expression of interleukin IL-1a, IL-1b, IL-6, tumor necrosis factor TNFa, keratinocyte chemoattractant KC/CXCL1, granulocyte colony-stimulating factor, G-CSF and MCP-1." (PMID 27658624, 2016). "In conclusion, the current study clearly demonstrates that alpinetin can effectively inhibit the expression of TNF-α and IL-1β in DSS-induced mouse colitis." (PMID 27321991, 2016). "GA regulates the levels of inflammatory mediators such as IL-6, TNF-α, and IL-1β in DSS-induced colitis in mice." (PMID 27110761, 2016). "A438079 treatment significantly decreased levels of TNF and IL-1β in colonic tissues of the mice with colitis, in concordance with inhibition of NF-κB and inflammasome pathways in colon tissues." (PMID 26739809, 2016).
colitis (continued). "Another interesting finding of our present study is observation concerning the influence of induction of colitis and administration of ghrelin on mucosal concentration of proinflammatory cytokines, IL-1β, and TNF-α." (PMID 27598133, 2016). "In animals with colitis, administration of ghrelin for six days resulted in more than a four-fold reduction in IL-1β in colonic mucosa; whereas concentration of TNF-α was reduced twice." (PMID 27598133, 2016). "Administration of obestatin at the dose used partly reversed the colitis-evoked increase in mucosal concentration of IL-1β and this effect was statistically significant in both periods of observation." (PMID 26798415, 2016). "Treatment with ghrelin after induction of colitis has inhibited a rise in mucosal IL-1β and TNF-α concentration." (PMID 27598133, 2016). "MOS administration attenuated colitis-related increase of Coliforms, normalized colonic muc2 expression and attenuated local expression of proinflammatory cytokines IL-1a, IL1b, IL6, KC, G-CSF and MCP1 as well as toll-like receptor TLR4 and NLRP3 inflammasome." (PMID 27658624, 2016). "Administration of ghrelin after induction of colitis led to faster regeneration of the colonic wall and reduction in colonic levels of IL-1β, TNF-α, and myeloperoxidase." (PMID 27598133, 2016). "Rifaximin administered alone caused a partial decrease in the level of IL-1β and TNF-α in colonic mucosa of animals with colitis." (PMID 27433160, 2016). "So, while circulating TNFα and IL-17 levels seem to correlate with the DSS colitis clinical course, IL-1β, and IL-10 mainly correlate with the histological damage that tends to become chronic." (PMID 26973525, 2016). "The results revealed that Acer3 knockout significantly augmented the colitis-induced increases in the mRNA levels of Il-1β, Il-6, Tnf-α and Il-23a in colon, although Acer3 deficiency did not affect the basal mRNA levels of these inflammatory cytokines." (PMID 26938296, 2016). "Ip administration of IL-1β at day 15 after TNBS induced colitis led to 90% of colitis recurrence in the SASP treated group, 10% in the Sal B(L) treated group, and 20% in the Sal B(H) treated group." (PMID 27303297, 2016). "Our results also showed that Sal B-induced restoration of defective tight junction barrier function has a protective effect against IL-1β-induced colitis recurrence." (PMID 27303297, 2016). "Acer3−/− mice that survived DSS treatment showed more severe colitis, as evidenced by a greater colon shortening, higher levels of inflammatory cytokines (Il-1β, Il-6, Il-23a and Tnf-α), higher MPO activity and more severe pathological manifestations." (PMID 26938296, 2016). "Many of the inflammatory cytokines attenuated by FFAR2 and FFAR3, including C5, CCL1, CCL2, GM-CSF, IL-1α, IL-1β, ICAM-1 and TNF, are associated with colitis." (PMID 27667443, 2016). "The key effect of the 13 reference genes on quantifying relative mRNA expression of two target genes (TNF-α and IL-1β) in DSS-experimental colitis was investigated using comparative the ΔΔCt method." (PMID 27244258, 2016). "Compared to untreated colitis, both oral fucoidan extracts significantly lowered the levels of IL-1α, IL-1β, IL-10, MIP-1α, MIP-1β, G-CSF and GM-CSF." (PMID 26083103, 2015). "Data from murine experimental colitis models and human intestinal specimens reveal that elevated expression of IL-8 and IL-1β is central to the pathogenesis of IBD." (PMID 26484345, 2015). "Induction of colitis by watering with DSS solution led to a 3-fold increase in IL-1β concentration in colonic mucosa." (PMID 26713317, 2015). "The anti-inflammatory effects of oregano (carvacrol as major component) oil in mice with TNBS-induced colitis showed that some combinations lowered the amount of IL-1β and IL-6 cytokines." (PMID 28231227, 2015).